CRP (C-reactive protein)
Diseases named in the same sentence as CRP in open-access papers (continued):
Sharing a sentence is not in itself a finding about the gene and the disease.
Obesity (continued). "Obesity was also associated with higher levels of inflammatory markers, such as CRP and interleukin-6 (IL-6), indicating an increased inflammatory state." (PMID 39518325, 2024). "This decrease was associated with significant downwards trends in concentrations of C-reactive protein and lipopolysaccharide-binding protein, both notable inflammatory markers associated with obesity." (PMID 39184030, 2024). "Diet influences CRP, a significant inflammatory marker, which is correlated with the risk of obesity." (PMID 39599620, 2024). "Obesity, ferritin, and CRP levels are associated with an increased risk of ICU admission, while cancer is a strong predictor of mortality." (PMID 38572008, 2024). "First, CRP only contributes to a part of the association between diet and obesity, and further research is needed to investigate other potential mediators." (PMID 39599620, 2024). "A lower Shannon index has previously been associated with poor health status including obesity, inflammation (C-reactive protein, interleukin-6), sugary drinks, and diarrhea." (PMID 38924513, 2024). "Research in U.S. adults indicates positive association between food insecurity and obesity in some sub-populations and with higher levels of C-reactive protein." (PMID 38916806, 2024). "C-reactive protein (CRP) is an inflammatory biomarker that is linked to musculoskeletal pain in association with obesity, work-related stress, and rheumatism." (PMID 38786992, 2024). "Other studies provide evidence of an association between obesity and some inflammatory markers, such as interleukin-6 (IL-6), C-reactive protein (CRP), and tumor necrosis factor-α (TNF-α)." (PMID 38634087, 2024). "For the effects of television watching on CRP, 126 genetic variants were initially identified, with 43 SNPs controlled for obesity-related traits and 1 outlier identified by MR-PRESSO, resulting in a mean F-statistic of 37.88." (PMID 39088575, 2024). "First, the APOM gene expression in AT was negatively correlated to plasma CRP in individuals with overweight or obesity, indicating that adipose APOM is inversely associated with obesity-related low-grade systemic inflammation." (PMID 39303980, 2024). "They believe that GlycA is associated mostly with inflammation and carotid atherosclerosis, whereas high CRP was more associated with obesity." (PMID 38785970, 2024). "Women with obesity and polycystic ovary syndrome who had higher adherence to the MedDiet also had lower cardiometabolic risk factors, including reduced levels of CRP, insulin resistance, and fatty liver index." (PMID 38978699, 2024). "In obesity, accumulated free fatty acids (FFAs) can cause pathophysiological mechanisms leading to inflammation and increasing the CRP levels." (PMID 38685027, 2024). "CRP, serving as a marker of systemic inflammation, has been found in the research to be associated with various factors, including smoking, obesity, elevated levels of triglycerides, and periodontal disease." (PMID 38672972, 2024). "C-reactive protein is also raised in patients with obesity and predicts a risk of myocardial infarctions." (PMID 38202263, 2024). "CRP was associated with overweight/obesity (adjusted OR 2.3, 95% CI 1.3, 4.1) and HIV positivity (adjusted OR 2.1 95% CI 1.5, 3.0." (PMID 39775265, 2024). "Other inflammatory markers, part of the first rotating analysis factor, associated with systemic inflammation in patients with obesity i.e., CRP, hsCRP, and ESR, were increased in MUO versus HC." (PMID 38904913, 2024). "To assess the association between chronic low-grade inflammation and obesity, we measured the levels of hs-CRP, IL-6, and TNF-alpha." (PMID 39200519, 2024). "Overall obesity also demonstrated causal links with insulin resistance, circulating leptin levels, C-reactive protein levels and risk of severe insulin resistant type 2 diabetes." (PMID 38977823, 2024).
Obesity (continued). "Several studies have shown that elevated CRP is strongly associated with obesity as part of the metabolic syndrome." (PMID 39081789, 2024). "In the US, sitting for more than 4 h a day has been linked to increased BMI and obesity, contributing to elevated hs-CRP levels." (PMID 38542799, 2024). "The association between Obesity and inflammation, as demonstrated in this study with high CRP values in the Obese group, is well known." (PMID 36986451, 2023). "Correlate for increased risk of high CRP included obesity, smoking, female sex, physical inactivity, chronic conditions and high creatinine and HbA1c." (PMID 37379302, 2023). "Standardized residuals from three-way χ2 tests to study the association between RA and the comorbidities depression, obesity, and hypertriglyceridemia, measured at three different plasma CRP levels." (PMID 38455932, 2023). "The relative effects of obesity on serum CRP in the PA mutation carriers were different from that in the non‐carriers." (PMID 37493001, 2023). "Obesity is associated with mild chronic inflammation, characterized by increased levels of CRP, which is further linked to the development of IR." (PMID 37686722, 2023). "This variant is associated with obesity risk, obesity phenotype, and several obesity comorbidities such as impaired glucose homeostasis and increased lipid and C-reactive protein levels." (PMID 37674889, 2023). "The effects of obesity and central obesity on serum CRP concentration were smaller among the protein‐altering mutation carriers in the CRP (pinteraction = 0.008) and G6PC gene (pinteraction = 0.034) compared to the corresponding non‐carriers." (PMID 37493001, 2023). "C-reactive protein was associated with obesity as part of the inflammatory pathway, while the associated one-carbon metabolism biomarkers were folate and vitamin B12." (PMID 36520252, 2023). "In individuals with obesity, inflammatory markers such as IL-6, CRP, and TNF-α have been associated with the progression of discogenic back pain." (PMID 37959372, 2023). "Particularly, we observed a significant interaction effect between PA mutation burden in the CRP gene and obesity measured by BMI, as well as PA mutation burden in the G6PC gene and central obesity indexed by waist circumference." (PMID 37493001, 2023). "Studies have demonstrated CRP to be associated with obesity, increased waist circumference and systolic BP; these parameters can be used for identification and intervention in children and adolescents with high risk of atherosclerosis." (PMID 37008812, 2023). "Obesity is associated with high levels of inflammation which can be measured through interleukin-6 (IL-6) and C-reactive protein (CRP)." (PMID 37566728, 2023). "3.Higher CRP levels would statistically mediate the associations of higher baseline BMI levels (overweight, obesity, overweight + obesity) with elevated overall, cognitive-affective, and somatic depressive symptoms." (PMID 36462595, 2023). "Several other inflammatory indicators, including IL-1β, IL-6 and C-reactive protein (CRP) are also associated with obesity." (PMID 37241120, 2023). "Background and Objectives: An obesity-related elevated body mass index (BMI) across life is associated with chronic low-grade inflammation and increased levels of C-reactive protein (CRP) in blood." (PMID 38138192, 2023). "2.Higher baseline BMI levels (overweight, obesity, overweight + obesity) and CRP would be more strongly associated with elevated somatic rather than cognitive-affective depressive symptoms at follow-up." (PMID 36462595, 2023). "The third sensitivity analysis indicated that compared with the BMI category ‘normal weight + overweight’, there was an indirect effect of CRP on the association between obesity and elevated somatic symptoms (indirect effect: β = 0.003, 95% CI: 0.001, 0.007)." (PMID 36462595, 2023).
Obesity (continued). "Obesity is associated with a pro-inflammatory state with adipocytes releasing and signaling the release of many pro-inflammatory cytokines such as CRP and IL-6." (PMID 37836549, 2023). "Poorly controlled type 2 diabetes and obesity are also associated with inflammatory markers like the neutrophil lymphocyte ratio and the C-reactive protein/albumin rate." (PMID 37370958, 2023). "Obesity is also associated with chronic inflammation, indicated by elevated C-reactive protein (CRP) levels." (PMID 37850622, 2023). "We also found evidence for an association of overweight, obesity, and excess body weight (overweight + obesity) with increased levels of CRP at wave 6, independently of baseline CRP, sociodemographic, lifestyle, and illness-related factors." (PMID 36462595, 2023). "Obesity is a chronic inflammatory state associated with elevated CRP levels, a recognized marker of systemic inflammation." (PMID 36520252, 2023). "Serum concentrations of adipokines, leptin, adiponectin, visfatin and resistin and inflammatory markers associated with low-grade inflammation in obesity, CRP, IL-6, sE-selectin, sVCAM, sPECAM and VEGF, were similar in both groups, regardless of CK-18." (PMID 37189422, 2023). "The state of chronic inflammation associated with obesity is related to high levels of inflammatory cytokines such as IL-6, C-reactive protein (CRP), and TNF-α." (PMID 36909335, 2023). "Obesity creates a proinflammatory environment characterized by high levels of circulating interleukin-6, tumor necrosis factor-α, C-reactive protein, and a relative deficiency of protective immune cell types." (PMID 37901321, 2023). "Children with obesity also had a 2.8-fold higher risk of having inflammatory syndrome with increased CRP levels (p = 0.015, χ2 = 5.8, OR = 2.8, 95% CI: 1.2–6.5)." (PMID 36837520, 2023). "Both IL-6 and CRP levels were associated with the obesity characterized by an increase infat mass in normal weight participants." (PMID 37242271, 2023). "Other studies have linked obesity and weight change with CRP, APCS, ADIPOQ, C3 and other complement proteins, ORM1, and ORM222,34,36–38." (PMID 37794065, 2023). "Coexistent with the chronic state of meta-inflammation, obesity is found among the main factors associated with high CRP." (PMID 36678307, 2023). "Taken together, PCOS and HFD-fed rats are more likely to reduce energy expenditure and thus contribute to obesity, but CRP deficiency reverses this process." (PMID 37660067, 2023). "In a systematic review, seven out of nine countries reported that obesity was associated with elevated CRP." (PMID 36996088, 2023). "In this diet, high fiber intake leads to reduction in the levels of LDL, cholesterol, triglycerides, hypertension, CRP, and the risk of obesity and overweight, and improves insulin sensitivity and endothelial function." (PMID 36911829, 2023). "Accordingly, the third sensitivity analysis that compared obesity with ‘normal weight + overweight’ provided further evidence for a mediating role of CRP in the association between obesity and somatic depressive symptoms." (PMID 36462595, 2023). "That is, when analyzed jointly, overweight/obesity and high HbA1c levels were synergistically associated with an increased risk of hs-CRP, and the interactive effect was approximately twice as significant as the individual effect." (PMID 37215204, 2023). "An additional mechanism leading to increased GDM risk involves obesity-related chronic inflammation with increased serum levels of cytokines including BMI (body mass index), tumor necrosis factor alpha (TNFα) and C-reactive protein (CRP)." (PMID 37886954, 2023). "More research had proven that SUA had a tremendous correlation with inflammatory markers such as C-reactive protein and interleukin-6, which was extra intently associated with metabolic ailments (such as obesity)." (PMID 37547098, 2023).
Obesity (continued). "Obesity in turn causes a pro-inflammatory state systemically and blood concentrations of CRP, IL-6 and other cytokines have previously been associated with changed (increased) micro-structural MRI metrics of free water." (PMID 37861301, 2023). "In this line, a systematic review and meta-analysis of cross-sectional studies relating CRP and obesity demonstrated a strong association between CRP and BMI." (PMID 37504556, 2023). "In our study, 16.4% of children had increased CRP values, and these were significantly associated with obesity (percentiles for BMI above 95%)." (PMID 36837520, 2023). "Low gut microbial diversity occurs with obesity, insulin resistance, dyslipidemia, leukocytosis, and elevated levels of C-reactive protein (CRP), which are linked to breast cancer." (PMID 38133287, 2023). "There are some conditions, such as obesity, pregnancy, depression, and diabetes, that in some cases are associated with minor elevations in CRP." (PMID 38001962, 2023). "The link between CRP and the acute-phase response, its contribution to impaired insulin signaling pathway, and in part, its links with obesity-driven systemic inflammation can explain the association with insulin resistance." (PMID 37891561, 2023). "Obesity increases CRP levels and is linked to mitochondrial dysfunction in adipose tissue leading to decreased adiponectin synthesis." (PMID 36520252, 2023). "The patients showed typical signs of obesity-associated low-grade chronic inflammation characterized by elevated CRP, fibrinogen, and leptin levels and decreased levels of adiponectin." (PMID 37266430, 2023). "A study investigating the causal direction of the relationship between excessive adiposity and inflammation, especially focusing on CRP, reached the conclusion that greater adiposity caused by fat mass and obesity-associated genes led to higher CRP levels." (PMID 38001962, 2023). "They observed that a longer duration of obesity was associated with increased odds of very low grip strength and higher CRP levels; higher CRP was correlated with lower hand grip strength." (PMID 37803197, 2023). "This indicates that obesity is likely to be the driver of the association between excess body weight, CRP, and somatic depressive symptoms." (PMID 36462595, 2023). "Previous studies using common genetic variants have observed that genetic predisposition to higher serum CRP modified the obesity–CRP relationship among both European and Asian populations." (PMID 37493001, 2023). "This dysfunction is related to an increase in circulating inflammatory factors (C-reactive protein, chemokines, and cytokines), and when associated with obesity-related insulin resistance it is related to worse outcomes." (PMID 36833052, 2023). "Particularly, obesity and central obesity influenced the serum CRP levels to a lesser extent in the carriers of the PA alleles in the CRP gene and the G6PC gene compared to the non‐carriers." (PMID 37493001, 2023). "High levels of CRP were reported to be associated with high levels of oxidative damage in the DNA of patients with psoriasis, obesity, pancreatic cancer and cardiovascular diseases." (PMID 37112613, 2023). "Elevated plasma levels of CRP, or hs-CRP, have been reported to be linked to obesity and insulin resistance, with the latter being implicated in the association between obesity and periodontitis." (PMID 37798684, 2023). "Obesity is associated with higher plasma levels of interleukin-6 (IL-6), C-reactive protein (CRP), and lipopolysaccharide (LPS), and accordingly, driving mononuclear cells into a pro-inflammatory (M1) state." (PMID 37238973, 2023). "Among the identified factors with different expression, CRP was associated with obesity, chronic inflammation and lung cancer risk." (PMID 37929799, 2023).
Obesity (continued). "After stratification by obesity status, blood hemoglobin (r = −0.36, p = 0.019), haematocrit (r = −0.44, p = 0.003) and ultrasensitive CRP (r = −0.37, p = 0.016) were significantly associated with the change in insulin sensitivity in subjects without obesity." (PMID 36902180, 2023). "It was assumed that obesity-related inflammation is mainly associated with the secretion of adipocyte-specific IL-6-type cytokines, which stimulate hepatic production of CRP." (PMID 37242271, 2023). "The effects of obesity and central obesity on serum CRP concentration were smaller among the PA mutation carriers in the CRP (pinteraction = 0.008) and G6PC gene (pinteraction = 0.034) compared to the corresponding non‐carriers." (PMID 37493001, 2023). "Severe obesity (BMI > 30) is associated with elevated C-reactive protein (CRP), an objective marker of inflammation." (PMID 37627482, 2023). "The effect of obesity in elevating serum CRP was smaller in the rare mutation carriers than in the non‐carriers." (PMID 37493001, 2023). "Studies have proven that obesity not only leads to vascular inflammation but also exacerbates the development of the disease and the upregulation of C-reactive protein (CRP), leptin, resistin, etc., increasing the risk of atherosclerosis." (PMID 38149053, 2023). "Both depression and obesity are associated with increased C-reactive protein, tumour necrosis factor-α, interleukin-1, and interleukin-6 levels." (PMID 36002471, 2022). "Serum CRP concentrations have been consistently associated with obesity as well as with obesity-related alterarions in adults and children." (PMID 35217714, 2022). "This study intends to learn the possible association between serum micronutrients, CRP, and obesity among children and adolescents." (PMID 35379317, 2022). "Our results demonstrate that genetically determined changes in CRP production can affect the adipo-hepato axis, leading to the defects in lipid metabolism and an increased risk of obesity, but only in elderly individuals." (PMID 35207726, 2022). "After adjustment for demographic characteristics, chronic illnesses, and CRP, obesity class I was associated with a 1.11-fold (95 % 1.01 to 1.22), and obesity class II-III with a 1.31-fold (95 % 1.16 to 1.49) increased risk of depression." (PMID 35853559, 2022). "Since migrant Bangladeshis in the UK and other industrialized countries are at increasing risk of inflammatory disorders such as overweight/obesity, T2D and CVDs, we predicted that more years spent in the UK would increase levels of CRP." (PMID 35035976, 2022). "Liraglutide, a GLP-1 analogue closely related to semaglutide, has also been associated with significant reductions in CRP in people with obesity and/or type 2 diabetes." (PMID 36467859, 2022). "A possible mechanism of the associations between obesity and chronic diseases relies on the theory of inflammation and inflammatory markers such as C-reactive protein (CRP), tumor necrosis factor α (TNF-α), and interleukin 6 (IL-6)." (PMID 35501761, 2022). "Children with higher baseline levels of CRP were at higher risk of developing overweight/obesity during growth." (PMID 35379317, 2022). "An increase in C-reactive protein (CRP) levels, measured using a high-sensitivity CRP (hs-CRP) test, is associated with obesity and is correlated with early progression of carotid atherosclerotic activity." (PMID 35846851, 2022). "Clear educational inequalities in raised physiological risk biomarkers levels, particularly in blood pressure and C-reactive protein were seen in Russia and are partly explained by lifestyle factors, particularly obesity among women." (PMID 35428237, 2022). "CRP, IL-6, TNFα, and leptin are found to be elevated in individuals with obesity and are also strongly associated with the development of preeclampsia." (PMID 35348641, 2022).